STAT3 (signal transducer and activator of transcription 3)
Diseases named in the same sentence as STAT3 in open-access papers (continued):
Sharing a sentence is not in itself a finding about the gene and the disease.
tumor (continued). "Here, we performed a detailed mechanistic study using the dual approaches of inducible genetic KD and pharmacologic inhibition of STAT3 on MYC gene regulation, MB tumor growth and chemosensitivity." (PMID 37190167, 2023). "Mechanistically, we not only observed activation of the JAK/STAT pathway in EC tissues, but also demonstrated that LDLs promoted EC cell proliferation, migration, and invasion, as well as tumor growth by upregulating the phosphorylation of JAK2 and STAT3." (PMID 37900720, 2023). "EDX suppressed elevated plasma levels of IL-6, MMP-2, TF, and PAI-1 and elevated tumor tissue levels of PAR2, STAT3, cyclin D1, and Ki67 in Colon26-inoculated mice." (PMID 36751299, 2023). "The IL‐6/STAT3 signaling pathway is activated by IL‐17 and directly induces VEGF release to promote tumor angiogenesis." (PMID 36951443, 2023). "After CAR-T cells target tumor antigens, the JAK and STAT3/5 signaling pathways are immediately triggered by IL-2R β fragments, thereby augmenting the antitumor efficacy and in vivo persistence of T cells." (PMID 37457288, 2023). "L1 cell adhesion molecule has been demonstrated to facilitate ovarian cancer cell spheroid formation, tumor initiation, and chemoresistance by triggering FGFR1 and its downstream SRC/STAT3 pathway." (PMID 37750089, 2023). "In the tumor microenvironment, IL-6/JAK/STAT3 signaling pathway drives malignant cell proliferation, survival, invasion, and metastasis while strongly inhibiting the antitumor immune response." (PMID 36937841, 2023). "This modification was revealed to be pivotal for various key aspects of STAT3 signaling, including its cellular membrane localization, interaction with JAK2, Y705 phosphorylation, and ultimately, PRMT6-mediated tumor metastasis." (PMID 37813837, 2023). "First, our studies with kifunensine demonstrated that the activation of STAT3 and STAT1 was effectively down-regulated by the inhibitor, alongside with a reduced tumor cell pro-metastatic functions." (PMID 37830552, 2023). "Inducible knockdown of STAT3 and ACSL4 in a paclitaxel resistant TNBC cell line decreased tumor growth and membrane lipids in vivo, suggesting that acetylated-STAT3 promotes FAO-mediated chemoresistance." (PMID 37779896, 2023). "Unlike PINK1, the downstream Parkin has been reported to inhibit tumor angiogenesis through ubiquitination degradation of HIF-1α at lysine 477, and inhibiting JAK2/STAT3/VEGF pathways in osteosarcoma." (PMID 37407961, 2023). "Upon internalization by metastatic tumor cells, the micellar structure was destroyed, the encapsulated SIL was leaked to inhibit STAT3 phosphorylation, and OXA was released responsively to induce ICD in the highly reduced cytoplasmic environment." (PMID 37159612, 2023). "Consistent with the MDA-MB-231 data, STAT3 signaling was suppressed, and its Slug expression was also downregulated in tumor cells derived from 4T1-EHF tumor tissue." (PMID 37958443, 2023). "The powerful activities of interferon γ, as the prime inducer of PD-L1 expression, were found to be mediated by STAT3, and in addition, STAT1 activation was found to up-regulate the expression of PD-L1 by tumor cells." (PMID 37830552, 2023). "Our previous studies showed a high expression of IL-6/STAT3 pathway proteins in human PDAC specimens and promising results for tumor growth inhibition by blocking this signaling." (PMID 36495330, 2023). "A previous study demonstrated that IL-6 generated by TAMs induces upregulation of CD47 on hepatoma cells via the STAT3 signaling pathway, subsequently influencing TAM-mediated phagocytosis, promoting tumor progression in HCC, and leading to poor prognosis." (PMID 37305578, 2023). "We identified that CDK1 activates STAT3 to regulate tumor sphere formation and the expression of stemness-related genes CD44 and SOX2, as well as both CDK1 and STAT3, which are negatively correlated with the prognosis of PDAC patients." (PMID 37743465, 2023).
tumor (continued). "IL-6 induces the activation of STAT3 and NF-κB by CRP and specific acute phase response proteins, preventing apoptosis and thus promoting tumor cell proliferation." (PMID 37719018, 2023). "Extracellular Hsp70 is enhancing tumor growth and migration by promoting multiple pro-oncogenic pathways including the PI3K/Akt and phosphorylated STAT3 pathways." (PMID 36399258, 2023). "Previously, gankyrin was demonstrated to enhance hepatocarcinogenesis via STAT3 activation through SHP-1 inhibition and IL-6 upregulation in the tumor microenvironment." (PMID 36660927, 2023). "To evaluate the effect of ZQD on IL6/STAT3 signaling pathway, we measured cytokines and STAT3 phosphorylation in PC3 xenograft tumor." (PMID 37576403, 2023). "Conversely, a decrease in STAT3 signalling can enable MDSC differentiation into TAMs, which often becomes the dominant tumour-infiltrating myeloid cell population." (PMID 36161514, 2023). "TCAF2 in TPCs inhibited the expression and ion channel activity of TRPM8, promoting tumor cell EMT and metastasis via activation of the Wnt5a/STAT3 signaling pathway." (PMID 37635201, 2023). "Compared to controls, mice implanted with STAT3- or SRF-downregulated GBM TSs showed reduced normal tissue infiltration and tumor growth, and prolonged survival, indicating a therapeutic response." (PMID 37558923, 2023). "Table 4also shows the concentrations of STAT3, cyclin D1, and Ki67 in the normal tissue of UTR mice and in the tumor tissue of the water-treated group of Colon26-inoculated mice." (PMID 36751299, 2023). "The sustained activation of STAT3 and STAT5 can increase tumor cell proliferation and disease progression, it would be therapeutic targets for enhancing anti-tumor immunity." (PMID 37976136, 2023). "Our experimental data unequivocally demonstrated that the most potent bifunctional inhibitor, NK3, directly bonds to IDO1 and STAT3, exhibiting potent in vivo antitumor efficacy in both CT26 tumor-bearing mice and athymic nude mice." (PMID 37630387, 2023). "Additionally, astrocytes which express signal transducer and activator of transcription 3 (STAT3) contribute to BrM by regulating innate and specific immunity as well as establish gap junctions with metastases cells to enhance the growth ability and drug resistance of tumor cells." (PMID 37056723, 2023). "IL-6/STAT3 as well as the IL-2/STAT5 pathway activates downstream target genes to protect tumour cells from apoptosis, increase tumour cell proliferation, cell cycle progression, invasion, and metastasis, and are involved in drug resistance." (PMID 36980202, 2023). "Signal transducer and activator of transcription (STAT) proteins hold central function in the tumor immune response in TME, and STAT3 promotes a pro‐cancer inflammatory response via NF‐κB, implying that STAT3 links inflammation and cancer." (PMID 37347147, 2023). "WP1066, another STAT3 inhibitor in phase I clinical trial (ClinicalTrials.gov Identifier: NCT01904123), has been shown to directly enhance anti-tumor immunity by inhibiting TI-Treg function in mice bearing melanomas." (PMID 39872303, 2023). "SHP-1 is a candidate molecular target for anticancer drug development because it regulates tumor growth and progression by downregulating JAK/STAT3 signaling." (PMID 38203502, 2023). "STAT3 and STAT5 are majorly involved in the progression of cancer while STAT1 plays a crucial role in tumor suppression." (PMID 37803407, 2023). "The IL‐6 axis is frequently dysregulated in cancer, which promotes pro‐tumor effects such as cancer growth, migration, and metastasis by activating the IL‐6/JAK/STAT3 pathway." (PMID 36632988, 2023). "On the one hand, abnormal STAT3 expression in tumors is correlated with MDSC and Th17 levels, affecting DCs and thus affecting anti-tumor response." (PMID 36911202, 2023). "The present study showed that PIAS3, an upstream inhibitor of the STAT3 signaling pathway, is one of the mechanisms by which HUC-MSCs supernatants inhibit tumor cells." (PMID 37057281, 2023).
tumor (continued). "Q11 does not directly affect tumor cells but blocks the tumor‐promoting effect of microglia/macrophage (M/Mφ) in the tumor microenvironment through PPARγ‐mediated activation of the STAT‐1 and NF‐κB pathways and inhibition of the STAT‐3 and STAT‐6 pathways." (PMID 37283464, 2023). "Serum interleukin 6 (IL-6) decreased the expression of PTPRO by activating signal transducer and activator of transcription 3 (STAT3)/c-MYC/miR-25-3p axis, leading to PD-L1-induced immunosuppression to promote tumor growth." (PMID 38155974, 2023). "STAT3 is the leading member of the STAT family that mediates both the release of pro-carcinogenic SASP and the suppression of anti-tumor immunity." (PMID 37752122, 2023). "In general, it was displayed that higher expression of STAT1, STAT2, STAT3, STAT4, and STAT5A indicated a lower tumor purity." (PMID 36968603, 2023). "By inhibiting the STAT3/PKM2/SNAP23 pathway, ATL I reduces the production of IL-6 and extracellular vesicles in C26 tumor cells and can be used to treat cancer cachexia." (PMID 37241729, 2023). "miR-124 directly interacts and inhibits the signal transducer and activator of transcription 3 (STAT3) signaling pathway and acts as an immuno-therapeutic molecule in the GSC tumor microenvironment." (PMID 37508353, 2023). "Our study demonstrated that either KD, or inhibition of STAT3 with small molecule inhibitor WP1066, significantly increases apoptosis and suppresses subcutaneous MB tumor growth with a concomitant increase in the survival of tumor-bearing mice in vivo." (PMID 37190167, 2023). "And the deletion of Stat3 in CD8+ T cells leads to the impairment of cytotoxic function and the decrease of T cell number to accelerate tumor growth." (PMID 37234153, 2023). "STAT3 activation can promote the accumulation and aggregation of MDSCs, and its inhibition can suppress the level of MDSC in the tumor microenvironment and improve the therapeutic effects of anti-PD-L1." (PMID 36923251, 2023). "This was thought to be mediated through the suppression of STAT3 signaling pathway and its downstream genes BCL2, c-MYC, and Survivin, which affect tumor growth by inducing apoptosis." (PMID 37189618, 2023). "In addition to the inhibition of the Akt pathway, we also observed that betulinaldehyde had a significant inhibitory effect on the MAPK pathway and the STAT3 pathway, suggesting that it may play an anti-tumor role in terms of regulating multiple signaling pathways in cells." (PMID 36639415, 2023). "Stat3 is a converging point of multiple oncogenic pathways, the activation of which in CD8+ T cells can significantly improve the anti-apoptosis and tumor killing ability of CD8+ T cells." (PMID 37234153, 2023). "Several mechanisms have been described that mediate RIPK4’s tumor suppression such as the phosphorylation of PKP1 and STAT3." (PMID 36765696, 2023). "The gene expression profile in CMS3 TME of KRASmut shows upregulation of CD40, CTLA4, ARG1, STAT3, IDO, and CD274, making it a key regulator of immune suppression in TME regions surrounding the KRASmut tumor." (PMID 36831441, 2023). "IL‐6 activated STAT3‐signalling in skeletal muscles and adipose tissues resulted in tissue atrophy of CHX207 mice, similar to previous observations in C26‐tumour‐bearing mice." (PMID 36351437, 2023). "Here, metformin was shown to exert anti-tumor effects on several levels, including the reprogramming of cells within the tumor microenvironment via activation of AMPK and by inhibition of STAT3 and NF-κB." (PMID 37509121, 2023). "The LIF receptor complex, composed of LIF, LIFR, and glycoprotein 130 (gp130), is responsible for promoting tumor growth, progression, and metastasis through the direct effect of JAK/STAT3 and other downstream pathways, such as MAPK, AKT, and mTOR." (PMID 37103052, 2023). "We observed that blocking either PI3K/Akt or JAK/STAT3 signaling reduced both CSC1 and CSC2 cell clonal growth in the cocultures containing PDX tumor stromal cells." (PMID 36982542, 2023).
tumor (continued). "Using a tumor array containing intestinal tissue biopsies from CRC patients and adjacent normal tissue, we performed immunohistochemical staining for phospho-STAT3 (pTyr705)." (PMID 38375204, 2023). "We found the expression level of PCNA and p-STAT3 was decrease greatly in MDG group (p < 0.05 and p < 0.05) compared with MD group, indicating the inhibition of tumor proliferation and NF-κB/IL-6/STAT3 signaling downstream protein." (PMID 37818040, 2023). "CD36 was recently identified as a marker of tumor-infiltrating PMN-MDSCs, and it plays an immunosuppressive role in mediating STAT3 signaling in MDSCs." (PMID 36788538, 2023). "Silencing CDK1 or STAT3 suppressed tumor stemness properties, while overexpressing CDK1 or STAT3 showed the opposite effect." (PMID 37743465, 2023). "This long-lasting tumor immunity is likely mediated by an IL-10 signaling pathway specific for intratumoral CD8+ T cells, IL-10-induced STAT1 and STAT3 phosphorylation, and IFN-γ expression in intratumoral CD8+ T cells." (PMID 37629156, 2023). "Among them, STAT3 and NF-κB pathways are strongly activated so that IL-6 and CXCL8 act synergistically to promote the proliferation of tumor cells." (PMID 37700840, 2023). "Consistent with elevated IL-6, oxidative stress, STAT3 phosphorylation, and muscle wasting, we demonstrated elevated expression of key genes and protein levels of UPS and autophagy pathways in tumor-bearing mice compared to controls." (PMID 35847939, 2022). "STAT3 is constitutively activated in HCC cells and persistently promotes tumour progression through direct regulation of oncogenic gene expression." (PMID 35665592, 2022). "In this study, we tested LLL12B in TNBC cells and the results showed that targeting STAT3 with LLL12B induced apoptosis and suppressed colony formation, migration, and tumor growth in TNBC cells." (PMID 36009550, 2022). "Significantly, blocking STAT3 improved the antitumour immune responses against HCC and the tumour immune microenvironment, and induced antitumour immune memory." (PMID 35665592, 2022). "And then, GBM tumor cell-induced IL-6 activates STAT3 in astrocytes, which subsequently drives IL-6 to stimulate GBM tumor cells and further promotes STAT3 signals and enhances downstream events." (PMID 35572545, 2022). "NR1D1 was reported to be a tumor suppressor in OC, which retarded the growth of cancer cells by abrogating the JAK/STAT3 signaling pathway." (PMID 36003381, 2022). "Western blot analysis showed that tumor cells overexpressing PRADX had reduced levels of BLCAP and increased nuclear levels of phosphor(p)-STAT3." (PMID 35574370, 2022). "HSP70 also mediates the occurrence of tumor-promoting immune microenvironment through TLR4, NF-κB, STAT3, and other signal pathways." (PMID 35957827, 2022). "The inhibition of Stat3, by type I IFN signaling, impairs VEGF and MMP-9 production by neutrophils and suppresses tumor angiogenesis." (PMID 35158807, 2022). "Evidence has displayed that tumor‐derived G‐CSF and GM‐CSF accelerate IRF‐8 downregulation via STAT3‐ and STAT5‐dependent pathways." (PMID 35612789, 2022).
tumor (continued). "The IL6-STAT3 signaling pathway is essential in the inflammatory response of tumor tissues, and the IL6- STAT3 signaling pathway has been reported to promote the enrichment of PCSCs in PCa tissues treated with ADT." (PMID 35292057, 2022). "Based on our data demonstrating a role for STAT3 in regulating the Sox2 expression marker for the cancer stem cell population of Shh MB, we performed an in vivo study to determine whether inhibition of STAT3, prior to established tumor development, affects initiation and formation of Shh MB." (PMID 34482626, 2022). "It has been found that PBRM1 modulates HIF1a-VEGF signal and STAT3-Interferon signal and BAP1 promotes genomic instability and therefore accelerates tumor metastasis." (PMID 35439951, 2022). "We previously demonstrated the synergistic effects of dual targeting Ref-1/STAT3 axis in PDAC in vivo xenograft model and in KPC tumor cells." (PMID 35402225, 2022). "Relative to the treatment of oe-LINC00858 + sh-NC, the expression levels of RAD21 and PCNP, and phosphorylation levels of STAT3 and STAT5 in the tumor tissues were lower after treatment of oe-LINC00858 + sh-RAD21." (PMID 35468892, 2022). "FLU inhibited tumor angiogenesis—as evidenced by almost completely suppressing the level of CD31 and STAT3." (PMID 35008943, 2022). "Immunoblot analyses of tumor xenografts corroborated our in vitro findings and revealed decreased expression of phosphorylated ERK1/2, MEK1/2, and Stat3 in the combination treatment group compared to either monotherapy." (PMID 35897659, 2022). "Based on RNA sequencing analysis of the tumor, we observed the signaling pathway most affected by NTP was the IL‐6/JAK/STAT3 pathway, which was downregulated after treatment." (PMID 36176603, 2022). "Several tumor-related markers, including the KRAS signaling pathway, IL-6/JAK/STAT3 signaling pathway, and inflammatory response were identified, which were enriched in low-risk patients." (PMID 36244998, 2022). "In tumor cells, IL-6 enriched EVsMMA-MRC5 activates IL-6/JAK/STAT3 and TGFβ signaling, promoting EMT and the acquisition of pro-aggressive traits." (PMID 36266345, 2022). "The volume and weight of the transplanted tumor was measured, and the expression of p-JAK2 and p-STAT3 and cell apoptosis in the xenograft tumor tissues were detected." (PMID 35909161, 2022). "In further evaluation, it was found that zerumbone downregulated expression of Ki-67, CD-31, Bcl-2, and p-STAT3, and increased expression of SHP-1 mRNA and SHP-1 in tumor tissues collected from the experimental animals." (PMID 35805049, 2022). "Western blot analysis of the expression of KIT-mediated signalling pathways in tumour tissues demonstrated that cabozantinib treatment also decreased p-KIT, p-STAT3, p-AKT, p-mTOR, and p-ERK1/2 expression levels in vivo." (PMID 33833412, 2022). "This latter can differentiate into mature TAMs when the signal transducer and activator of transcription 3 (STAT3) are downregulated; additionally, M-MDSCs contribute to the immunosuppressive tumor microenvironment, promoting tumor metastasis." (PMID 35664746, 2022). "In vivo studies showed that Siglec-15 RNAi inhibited tumor growth and increased the CD4+/CD8+ ratio; however, this was offset by the overexpression of STAT1 and STAT3." (PMID 35769818, 2022). "STAT3 reprogram metabolisms through promoting FAO and inhibiting glycolysis in CD8+ Teffs, leading to suppression of anti-tumor response." (PMID 35062950, 2022). "Extracellular succinate induces tumor angiogenesis through SUCNR-1-mediated ERK1/2 and STAT3 activation resulting in upregulation of vascular endothelial growth factor (VEGF) expression." (PMID 36344992, 2022). "mPRα knockdown or overexpression was generated in LUAD cells, and the roles of mPRα in cAMP concentrations, the protein levels of STAT3 signaling factors, HIF1α, and VEGF, and LUAD cell migration, invasion in vitro and tumor growth in vivo were investigated." (PMID 35123491, 2022).